TLR6 (toll like receptor 6)
Diseases named in the same sentence as TLR6 in open-access papers (continued):
Sharing a sentence is not in itself a finding about the gene and the disease.
infection (67 papers, 2008 to 2025). The state of being infected such as from the introduction of a foreign agent such as serum, vaccine, antigenic substance or organism. "In contrast, TLR1, TLR3 and TLR5, expression was significantly downregulated, whereas TLR6 remained unchanged throughout the infection period." (PMID 41305370, 2025). "In leukocytes, expression of F13A1 (forming coagulation FXIII) correlated with TLR7, TLR9, RIG-I, MDA5, and LGP2, and with infection the correlations changed to TLR6 and CGAS." (PMID 40825056, 2025). "With infection, in platelets, associations changed and expression of F2RL3 and GP6 both positively correlated with TLR6, TLR9, RIG-I, MDA5, LGP2, and CGAS." (PMID 40825056, 2025). "As shown in previous studies, TLR6 was activated in the intestinal tissues in response to bacteria in this experimental infection, promoting increased release of immune inflammatory markers." (PMID 40869997, 2025). "TLR6 levels showed a significant increase during the first 35 weeks of infection in a time-dependent manner, followed by a gradual decrease." (PMID 38310631, 2024). "Our study found fluctuations in serum TLR6 levels during various infection durations and pathological lesions." (PMID 38310631, 2024). "ASFV infection can activate the RLR and TLR signaling pathways, while TLR4 and TLR6 are significantly downregulated after infection." (PMID 37048502, 2023). "SS1 strain infection induced TLR6 mRNA transcript up to 8.2-fold (P < 0.0001); however, the changes in expression levels of TLR1 and TLR2 were either insignificant or scarcely downregulated." (PMID 36317079, 2022). "R-LD infection results in the NF-κB activation via ligation with TLR2/TLR6, leading to up-regulation of miR-466i in the initial hours of infection, whereas inducing high amounts of IL-10 in late hours." (PMID 35925884, 2022). "Most noticeably, Nsp1-K164A/H165A infection had least effects on the expressions of proinflammatory markers, such as Mx2, Ifit3, Tlr6, Cxcl10, and Nfkb1." (PMID 36357440, 2022). "In applied contexts, activation of TLR6 following V. alginolyticus△vscC strain infection in oyster hemocytes carries the implications of potential use of attenuated strains in host immune priming in an immunologically mild manner." (PMID 34621277, 2021). "We anticipated a relatively mild immune mechanism, wherein Toll-like receptor 6 (TLR6) orchestrated defense strategies against infection by the V. alginolyticus△vscC strain through activation of downstream signaling pathways." (PMID 34621277, 2021). "Among the asymptomatic mice, virus was detected in the brain as early as day 1 post-infection for the DV2-infected TLR6-/- mice and the virus persisted in the brains of the mice till the endpoint of the experiment." (PMID 26226614, 2015). "The overall survival probability of wild-type mice during DV2 infection was lower than TLR6-/- mice." (PMID 26226614, 2015). "DV2 was able to replicate in the brain of TLR6-/- mice from day 1 post-infection while DV2 was only detected in the brain of DV2-infected wild-type mice from day 3 post-infection." (PMID 26226614, 2015). "Although consistent viremia was detected in the mice infected at 1–2 day old for both wild-type and TLR6-/- mice, the virus titers were observed to decrease as the day of infection progressed." (PMID 26226614, 2015). "Of note, although the infection of BCG augmented the expression of TLR6 and TRAF6 at protein levels, the expression levels were dramatically repressed in BCG-infected cells that were transfected with miR-124 mimic (p<0.05)." (PMID 24705038, 2014). "Compared to wild-type mice, resistance to primary infection and to re-challenge was similar in TLR9-deficient or TLR6-deficient mice; it was greatly increased in TLR2-deficient mice but impaired in TLR3- or TLR4-deficient mice." (PMID 23853597, 2013). "S. suis wild-type strain induced significant up-regulation of TLR2 and TLR6 mRNA by DCs at 16 h and 10 h of infection, respectively." (PMID 21635729, 2011).
infection (continued). "RANTES, CC-CKR-3, TLR6 and IL-6 were highly up-regulated in Jurkat and K562 cells upon infection with dengue virus." (PMID 19117515, 2008). "Rather, the downregulation of TLR4 and TLR6 in response to T15 and S10 infection, respectively, as well as the downregulation of expression of the adapter protein MYD88 during 8067 and T15 infection, was seen (albeit at low-fold changes, especially during T15 infection)." (PMID 38276150, 2023). "The results of the co-immunoprecipitation experiment showed TLR1 and TLR6 were better able to bind to a TLR2 primary antibody following infection with three strains of M. bovis compared with controls, which indicated that there was a crosstalk between TLR1/TLR2 and TLR2/TLR6." (PMID 35464378, 2022). "In addition, testosterone increases TLR6 expression associated with the epigenetic modification caused by TLR6 promoter methylation and decreases TLR8 expression in the liver of Plasmodium chabaudi-infected mice, contributing to the persistence of infection." (PMID 36551196, 2022). "TLR6 may form heterodimers with TLR2, which can recognize viral proteins and enhance infection, leading to increased TLR6 expression." (PMID 36171749, 2022). "When TLR-6 expression is observed after 24 h of infection, a statistically significant overexpression of this molecule is evidenced for all stimulated conditions, for serotypes a (p < 0.0001), b (p = 0.0009), and c (p < 0.0001) compared to the non-infected control." (PMID 33802988, 2021). "Once internalized, mycobacterial specific N-glycolyl MDP is recognized and activates NOD2, leading to synergistic interactions with TLRs and TLR heterodimers (TLR2, TLR1, and TLR6) to promote downstream activation of NF-κB signaling and a pro-inflammatory response to infection." (PMID 34485444, 2021). "However, the addition of rapamycin increased the expression of Mtb-induced TLR-6 expression but inhibited the expression of NF-κB and mTOR in U937 macrophage-like cells of all three conditions of infection." (PMID 30356420, 2018). "In addition, significantly higher expression of TLR6 in CH than in the period prior to infection, TLR8 in AH than in the SLAH/SOI phase, and TLR10 in CH than in AH were apparent in both PBMC and liver biopsies." (PMID 30581424, 2018). "In humans, polymorphism in TLRs (TLR1, NOD2, TLR6 and TLR10) might be associated with the reduced production of cytokines after infection and finally less responsiveness of macrophages to infection." (PMID 29321921, 2018). "This may suggest that IL-6 and TNF-α in the sera at the later part of infection was mostly contributed by DV NS1 protein activating TLR6." (PMID 26226614, 2015). "In addition, it was noticed that IL-6 up-regulation in the sera of DV2-infected TLR6-/- mice subsided by day 5 post-infection while that of responsive wild-type mice remained up-regulated." (PMID 26226614, 2015). "Some of the mice, both DV2-infected wild-type and TLR6-/-, remained unresponsive to the infection." (PMID 26226614, 2015). "TLR6 was found to be up-regulated by PBMC on day 3 post-infection." (PMID 26226614, 2015). "Thus, high activation of innate immunity receptors (TLR4, TLR6) and inflammatory cytokines (such as pro-IL-1β) in Swiss mice during the acute phase of infection may contribute to the low parasite burden." (PMID 38896633, 2024). "Similarly, in infection by yeast cells, MR, TLR6, CR3 and TLR2 receptors are overexpressed." (PMID 35628694, 2022). "However, transcription of TLR6 was unchanged post infection with SS2 ZY05719." (PMID 30581435, 2018). "The survival plots of the DV2-infected wild-type and TLR6-/- mice intercept, indicating that the probability of survival for one population of the mice were higher for a period of time during DV infection but became lower compared to the other population as the infection progresses." (PMID 26226614, 2015).
infection (continued). "In leukocytes, PLAUR positively correlated with RIG-I and MDA5 which changed to TLR3, TLR6, and TLR8 with infection; PLAU, on the other hand, lost its correlation with TLR4 and TLR5 with COVID19." (PMID 40825056, 2025). "With infection, expression of certain PRRs in platelets increased (TLR9, RIG-I, and CGAS), while in leukocytes, they decreased (TLR6, TLR8)." (PMID 40825056, 2025). "Here, we observed higher TLR2, TLR4, TLR5, TLR6, TLR8, TLR9, Myd88, NLRP3, ASC, and TNF-α mRNA expression at seven weeks after infection by S. mansoni in BALB/c and C57BL/6 mice compared to Swiss mice." (PMID 38896633, 2024). "Our study showed that in the early stage of S. mansoni infection (two weeks post infection) Swiss mice showed higher expression of TLR4, TLR6 and Myd88 mRNA in the liver than BALB/c and C57BL/6." (PMID 38896633, 2024). "Hence, we proposed that TLR6 agonists may activate the inflammatory pathway and subsequently promote the elimination of pathogens by the host immune system during the later stages of infection." (PMID 38310631, 2024). "No increase was observed in the transcription of Toll-like receptors (TLR2, TLR4, TLR6) and TLR adaptor protein MYD88 during infection with any of the examined S. suis strains." (PMID 38276150, 2023). "Upon infection with H. pylori J99 strain, we noted that TLR1, TLR2, and TLR6 mRNA transcripts were merely upregulated by approximately 2-fold." (PMID 36317079, 2022). "S. schenckii yeast infection kinetics found an increase in the production of TLR6, MR, CR3, and TLR2 receptors starting 2 h post-infection, with a maximum expression at 10 h, compared to the control group of uninfected cells." (PMID 35628694, 2022). "The expression of IL-1β, IL-6, IL-8, IL-18, TNF-α, MMP-9, RANKL, TLR-2, TLR-4, TLR-6, thymic stromal lymphopoietin (TSLP), and ICAM-1 was evaluated by qPCR at 2 and 24 h after infection." (PMID 33802988, 2021). "The exclusive up-regulation of TLR6 and 7 in the caecum of VIT and TLR21 in VIC argues for a regulative effect against inflammation in protected birds following infection." (PMID 34579197, 2021). "Two small pathways (first: LAMP-TLR2/TLR6-MyD88-MKK6-AP1-IL1B; second: LAMP-TLR8-MyD88-IRF5-RANTES) were identified using the KEGG database, indicating that DEGs related with MO infection were mapped to the TLR signaling pathway." (PMID 32639963, 2020). "gga-miR-146c was functional by regulating TLR6/MyD88/NF-κB pathway and targeting MMP16 to manipulate cell cycle, multiplication, and apoptosis in host defense of MG-HS infection." (PMID 31137698, 2019). "Transcriptional levels of neutrophil TLR2 and TLR4 at 3 h post-infection with SS2 ZY05719 were 2.9- and 2.5-fold that of untreated neutrophils, whereas that of TLR6 was unchanged." (PMID 30581435, 2018). "The microarray data indicated that TLR expression in chicken B cells exhibited a distinct pattern in response to vvIBDV infection, with decreases in the expression of TLR2, TLR6, and TLR7." (PMID 28086922, 2017). "Our results showed that F. hepatica infection significantly downregulated the mRNA expression of TLR1, TLR5, TLR6, TLR7 and TLR10 in PBMC at the acute stage of infection (T2)." (PMID 27661612, 2016). "However, TLR6−/− mice infected with L. major did show significant differences in lesion size compared to WT mice, with healing occurring earlier resulting in significantly smaller lesions in the later stages of infection (weeks 11–12) (Week 11: U = 2, P = 0.0047; Week 12: U = 0, P = 0.0012)." (PMID 27716391, 2016). "Mock-infected and DV2-infected PBMC were harvested on day 3 post-infection and stained for TLR2/TLR6 and CD14." (PMID 26226614, 2015). "In general for both wild-type and TLR6-/- mice, the DV NS1 protein level started to decrease from day 4 post-infection and on day 5, DV NS1 protein level in one of the wild-type mice fell close to the relative OD of the mock-infected mice." (PMID 26226614, 2015).
infection (continued). "Our results suggest that TLR1 and TLR6 mediate the innate immune response to M. haemolytica while TLR2 and TLR4 mediate response to infection by IBR and other viruses." (PMID 26121276, 2015). "TLRs are among the most important PRRs for the recognition of mycobacterial PAMPs during the early stages of infection, particularly the cell surface TLR2 (acting alone or as a heterodimeric complex with TLR1 or TLR6) and TLR4 receptors." (PMID 22384131, 2012). "Macrophages harvested from TLR1−/− and TLR6−/− mice expressed TNF, IL-6, MCP-1, and IL-10 in response to LVS infection in vitro at comparable or higher levels than B6 mice." (PMID 19936231, 2009). "TLR6 (respectively) and TLR7 (respectively) were significantly overexpressed in infection-derived EVs compared to control-derived EVs, while TLR3 (respectively) was expressed but significantly unchanged within EVs." (PMID 36979955, 2023). "All turkeys that received vaccination and infection showed consequences on upregulation of TLR1B, TLR2B, TLR4, TLR6 and TLR7, whereas in chickens of the equivalent group, TLR1B, TLR2B and TLR21 were found to be increased in contrast to TLR4 and TLR7 which were decreased." (PMID 34579197, 2021). "The lack of differential expression of other TLR genes in this study is in contrast to a previous study of transcriptomic response of ovine PBMC conducted by our group, where TLR1, TLR5, TLR6, TLR7 and TLR10 were downregulated in PBMC at the acute stage of infection." (PMID 34616397, 2021). "As the disease kinetics in TLR1−/− or TLR6−/− mice do not match that of TLR2−/− mice, this strongly suggests that the role for TLR2 during infection does not require either TLR1 or TLR6." (PMID 27716391, 2016). "Whilst increased resistance to L. major by mice lacking TLR6 was observed, TLR6−/− mice did not have any reduced disease severity or parasite burdens upon infection with L. mexicana in this study." (PMID 27716391, 2016). "Infections with mice lacking either TLR1 or TLR6, the known co-receptors for TLR2, did not present with the same disease phenotype as TLR2−/− mice, suggesting that neither is crucial for the TLR2-mediated control of infection with L. major or L. mexicana." (PMID 27716391, 2016). "The amount of IL-6 produced by DV2-infected TLR6-/- murine peritoneal macrophages was higher than that of the mock-infected, suggesting that the stimulation by DV NS1 protein only contributed partially to the amount of IL-6 detected in the DV2 infection." (PMID 26226614, 2015). "By day 4 post-infection, virus can no longer be detected in the sera of mice except for one TLR6-/- mice whose serum detected presence of DV2 on day 5 post-infection." (PMID 26226614, 2015). "Viral loads were detected in the brain of the TLR6-/- mice on day 1 post-infection but not for wild-type mice." (PMID 26226614, 2015). "Like what was observed for TLR6, TLR2 was found to be up-regulated by PBMC on day 3 post-infection." (PMID 26226614, 2015). "The mRNA expression of TLR1, TLR2, TLR4 and TLR6 of C. burnetii NM stimulated PBMCs derived from naive and infected goats at day 35 equalled the expression as prior infection (data not shown)." (PMID 25279829, 2014). "The survival rate of these mice infected i.n. with LVS was indistinguishable from the survival rate of control mice indicating that neither TLR1 nor TLR6 is exclusively required for host resistance to LVS infection." (PMID 19936231, 2009). "The expression of the TLR3, TLR5, and TLR6 genes in the liver tissue of infected rhesus macaques was downregulated in the early phase of HEV1 Sar-55 and HEV3-JN83748 infections, while TLR3 gene expression was only upregulated at peak infection and declined during HEV3 infection." (PMID 32731452, 2020). "This may suggest that TLR6 acts to exacerbate infection with L. major, but not L. mexicana, or may perhaps be a reflection of the more chronic nature of L. mexicana infection, and in the reduced Th1 response involvement when compared to L. major." (PMID 27716391, 2016).
infection (continued). "Due to our inability to exclude redundancy between TLR1 and TLR6 in these infection models, we are unable to rule out the possibility that TLR2 may utilise either TLR1 or TLR6 co-receptor involvement in these settings." (PMID 27716391, 2016). "Together, these results suggest that the higher survivability of the TLR6-/- mice during DV infection could be due to their non-responsiveness to DV NS1 protein." (PMID 26226614, 2015). "Moreover, signaling through TLR2 does not depend exclusively on TLR1 or TLR6 during F. tularensis LVS infection." (PMID 19936231, 2009). "Similarly, the non-encapsulated strain activated both TLR2 and TLR6 within 10 h of infection." (PMID 21635729, 2011). "A limitation of this study is the lack of in vivo validation of the role of hepatocyte TLR2:TLR6 and TLR5 in mediating the hepcidin response and subsequent hypoferremia during infection." (PMID 40182015, 2025). "Importantly, in Tlr6−/− control embryos without BCW challenge, the loss of TLR6 increased the number of cortical neurons, suggesting that an endogenous TLR signal regulates normal neurodevelopment in the embryo and that BCW released from maternal infection antagonizes that signal." (PMID 37052506, 2023). "In our study, TLR2 (but not TLR6) was found to be up regulated in both S. aureus WCH-SK2WT and WCH-SK2SCV infection (i.e., intracellular WCH-SK2WT and WCH-SK2SCV, and extracellular WCH-SK2SCV infection)." (PMID 28083514, 2016). "Another example is the role of TLR6 and TLR2 in the antiviral response against respiratory viral disease (RSV), where infection increases TLR2 expression and the absence of TLR2 or TLR6 leads to a higher viral load and lower production of pro-inflammatory cytokines." (PMID 40573281, 2025). "As a result, the expression of TLR2 and TLR10 experienced no obvious alterations during infection, and the expression of TLR5 and TLR6 increased slightly, whereas the expression of TLR4 was downregulated significantly, which were consistent with previous reports." (PMID 33414472, 2021). "In addition, DV2-infected PBMC expressed higher level of TLR6 and TLR2 on day 3 post-infection but not day 1 and day 2 post-infection." (PMID 26226614, 2015). "However, an ongoing infection with gram-negative bacteria might sensitize the lung towards gram-positive stimuli as TLR2 and TLR6 expressions are upregulated by LPS." (PMID 21547259, 2011).